CACTIN (cactin, spliceosome C complex subunit)
Description:
Plays a role in pre-mRNA splicing by facilitating excision of a subset of introns. Required for the splicing of CDCA5/Sororin, a regulator of sister chromatid cohesion. Involved in the regulation of innate immune response. Acts as a negative regulator of Toll-like receptor, interferon-regulatory factor (IRF) and canonical NF-kappa-B signaling pathways. Contributes to the regulation of transcriptional activation of NF-kappa-B target genes in response to endogenous pro-inflammatory stimuli.
Synonyms: C19orf29; NY-REN-24; fSAPc
Tractability: Small molecule: a structure with a bound ligand is known. PROTAC: UniProt records ubiquitination sites on it; ubiquitination databases record sites on it; its protein half-life has been measured.
Gene: Protein-coding gene on chromosome 19 (3,610,645 to 3,626,815, reverse strand). Ensembl gene ENSG00000105298.
Subcellular location: Nucleus; Cytoplasm, cytosol
Subcellular location (Human Protein Atlas): Nuclear speckles; Nucleoplasm; Cytosol
Pathways (Reactome):
Metabolism of RNA: mRNA Splicing - Major Pathway
Gene Ontology:
Molecular function: protein binding; RNA binding
Biological process: cellular response to interleukin-1; cellular response to lipopolysaccharide; cellular response to tumor necrosis factor; mRNA splicing, via spliceosome; negative regulation of canonical NF-kappaB signal transduction; negative regulation of interferon-beta production; negative regulation of interleukin-8 production; negative regulation of lipopolysaccharide-mediated signaling pathway; negative regulation of protein phosphorylation; negative regulation of toll-like receptor signaling pathway; negative regulation of tumor necrosis factor production; negative regulation of type I interferon-mediated signaling pathway; mRNA cis splicing, via spliceosome; negative regulation of innate immune response
Cellular component: catalytic step 2 spliceosome; nuclear speck; nucleoplasm; nucleus; spliceosomal complex; U2-type catalytic step 1 spliceosome; U2-type catalytic step 2 spliceosome; cytoplasm; cytosol
Genetic constraint (gnomAD): Loss-of-function variants: 20 observed, 62.44 expected, observed/expected ratio (o/e) 0.32, 90% interval 0.22 to 0.47. The synonymous counts are far from expectation, so gnomAD's model fits this gene poorly and the ratio says little. Missense variants: 897 observed, 1,013.9 expected, observed/expected ratio (o/e) 0.88, 90% interval 0.84 to 0.94. Synonymous variants: 549 observed, 423.49 expected, observed/expected ratio (o/e) 1.3, 90% interval 1.21 to 1.39.
Homologues: Orthologues: chimpanzee CACTIN (99% identical), macaque CACTIN (98% identical), dog CACTIN (93% identical), pig CACTIN (92% identical), guinea pig CACTIN (90% identical), mouse Cactin (87% identical), rat Cactin (86% identical), tropical clawed frog cactin (77% identical), zebrafish cactin (72% identical), Drosophila melanogaster cactin (48% identical), Caenorhabditis elegans cacn-1 (35% identical). Paralogues in human: MARVELD3 (9% identical), PQBP1 (6% identical).
Diseases named in the same sentence as CACTIN in open-access papers:
CACTIN is named in the same sentence as 9 diseases in open-access papers, as found by Europe PMC text mining. Sharing a sentence is not in itself a finding about the gene and the disease.
CACTIN shares sentences with these, for which no sentence is quoted: breast carcinoma (2 papers); basal cell carcinoma (1); cancer of female genital organs (1); cancer of male genital organs (1); gastric cancer (1); HIV-1 infection (1); renal carcinoma (1); skin cancer (1); tumor (1).